OR6A2 (olfactory receptor family 6 subfamily A member 2)
Description:
Odorant receptor.
Synonyms: OR11-55; OR6A1; OR6A2P; I7
Tractability: Antibody: UniProt places it where antibodies can reach, with medium confidence; UniProt predicts a signal peptide or a membrane-spanning region; its Gene Ontology location is reachable by antibodies, with medium confidence.
Gene: Protein-coding gene on chromosome 11 (6,791,736 to 6,799,689, reverse strand). Ensembl gene ENSG00000184933.
Subcellular location: Cell membrane
Pathways (Reactome):
Sensory Perception: Expression and translocation of olfactory receptors
Gene Ontology:
Molecular function: G protein-coupled olfactory receptor activity; G protein-coupled receptor activity; olfactory receptor activity
Biological process: adenylate cyclase-activating G protein-coupled receptor signaling pathway; detection of chemical stimulus involved in sensory perception of smell; positive regulation of NLRP3 inflammasome complex assembly; sensory perception of smell; signal transduction; G protein-coupled receptor signaling pathway
Cellular component: plasma membrane; membrane
Genetic constraint (gnomAD): Loss-of-function variants: 7 observed, 13.81 expected, observed/expected ratio (o/e) 0.51, 90% interval 0.29 to 0.95. The upper end of that interval is the gene's LOEUF score, 0.95, which puts it in group 4 of 6, group 1 being the genes least tolerant of losing a copy. Missense variants: 431 observed, 421.45 expected, observed/expected ratio (o/e) 1.02, 90% interval 0.94 to 1.11. Synonymous variants: 162 observed, 161.84 expected, observed/expected ratio (o/e) 1, 90% interval 0.88 to 1.14.
Homologues: Orthologues: chimpanzee OR6A2 (99% identical), mouse Or6a2 (90% identical), rabbit OR6A2 (90% identical), rat Or6a2 (90% identical), guinea pig OR6A2 (89% identical), pig OR6A2 (88% identical). Paralogues in human: OR6Y1 (55% identical), OR6B1 (54% identical), OR10C1 (45% identical), OR10A4 (44% identical), OR10A5 (43% identical), OR5V1 (43% identical), OR10A7 (43% identical), OR13C4 (43% identical), OR13D1 (43% identical), OR2G6 (43% identical), OR2H2 (43% identical), OR2D3 (42% identical), and 80 more.
Diseases named in the same sentence as OR6A2 in open-access papers:
OR6A2 is named in the same sentence as 3 diseases in open-access papers, as found by Europe PMC text mining. Sharing a sentence is not in itself a finding about the gene and the disease. The quoted sentences say what the papers report.
atherosclerosis (2 papers, 2022). A disease characterized by the build-up of fatty material and calcium deposition in the arterial wall resulting in partial or complete occlusion of the arterial lumen. "Since knocking out Olfr2 reduces atherosclerosis, Olfr2 and, by extension, OR6A2, are potential therapeutic targets for the prevention and treatment of atherosclerosis." (PMID 36311776, 2022). "Although the functions of several olfactory receptors expressed outside the olfactory epithelium have been identified, the present study unexpectedly discovered the crucial role of OLFR2 and its human ortholog OR6A2 in atherosclerosis progression." (PMID 35864109, 2022). "Triggering human OR6A2 or its mouse orthologue Olfr2 with their cognate ligand octanal induces inflammasome assembly and the secretion of IL-1β, which exacerbates atherosclerosis." (PMID 36311776, 2022). "For example, OR6A2 inhibitor combining with lipid-lowering drugs could have more potent effects in atherosclerosis therapy than using lipid-lowering drugs alone." (PMID 35864109, 2022). "Given that OR6A2 lies upstream of the NLRP3 inflammasome, OR6A2 could serve as a potential therapeutic target for inflammation initiated by lipid, especially, for the prevention, treatment, and reversal of atherosclerosis." (PMID 35864109, 2022).
aneurysm (1 paper, 2024). Bulging or ballooning in an area of an artery secondary to arterial wall weakening. "In particular, deficiency of the OR6A2 ortholog, Olfr2, in murine models mitigates aneurysm development and progression." (PMID 39768700, 2024).
aortic atherosclerosis (1 paper, 2024). A atherosclerosis that involves the aorta. "Inhibition of the OR6A2 (Olfr2) receptor may also have a role against aortic atherosclerosis, vascular wall inflammation and the ECM/VSMC disruption frequently observed in these cases, as relevant studies with OR6A2 (Olfr2)-deficiency show a halt in the progression of aortic dilatation." (PMID 39768700, 2024).